AMMECR1 (AMMECR nuclear protein 1)
Synonyms: AMMERC1; MFHIEN
Tractability: PROTAC: ubiquitination databases record sites on it.
Gene: Protein-coding gene on chromosome X (110,194,186 to 110,440,318, reverse strand). Ensembl gene ENSG00000101935.
Subcellular location: Nucleus
Subcellular location (Human Protein Atlas): Nucleoplasm; Mitochondria
Gene Ontology:
Molecular function: protein binding
Cellular component: nucleoplasm; nucleus
Homologues: Orthologues: chimpanzee AMMECR1 (100% identical), macaque AMMECR1 (100% identical), rabbit AMMECR1 (99% identical), dog AMMECR1 (99% identical), guinea pig AMMECR1 (98% identical), rat Ammecr1 (97% identical), mouse Ammecr1 (97% identical), pig AMMECR1 (86% identical), tropical clawed frog ammecr1 (78% identical), zebrafish ammecr1 (77% identical), Drosophila melanogaster CG5902 (41% identical), Caenorhabditis elegans R166.3 (28% identical). Paralogues in human: AMMECR1L (63% identical).
Diseases named in the same sentence as AMMECR1 in open-access papers:
AMMECR1 is named in the same sentence as 17 diseases in open-access papers, as found by Europe PMC text mining. Sharing a sentence is not in itself a finding about the gene and the disease. The quoted sentences say what the papers report.
Alport syndrome (3 papers, 2017 to 2020). A rare renal disease characterized by glomerular nephropathy with hematuria progressing to end-stage renal disease (ESRD), frequently associated with sensorineural deafness, and occasionally with ocular anomalies. "Notably, a point mutation in the human ortholog of SPAC688.03c, AMMECR1, is associated with Alport syndrome (A), mental retardation (M), midface hypoplasia (M), and elliptocytosis (E)." (PMID 29550859, 2018).
elliptocytosis (3 papers, 2017 to 2019). "Recently, variants in AMMECR1 were observed in individuals with midface hypoplasia, hearing impairment, elliptocytosis, and nephrocalcinosis (OMIM 300990)." (PMID 30809043, 2019). "With evidence to support an association between AMMECR1 and elliptocytosis, blood films were requested on the brothers at ages 10 and 4, and both smears were reported blindly." (PMID 27811305, 2017).
Hearing impairment (2 papers, 2017 to 2019). A decreased magnitude of the sensory perception of sound. "This may suggest that AMMECR1 is pathogenically implicated in hearing loss, either alone, or as a modifier gene to COL4A5 due to their direct protein–protein interaction." (PMID 27811305, 2017).
nephrocalcinosis (2 papers, 2017 to 2019). Nephrocalcinosis is a disorder that occurs when too much calcium is deposited in the kidneys. "We conclude that AMMECR1 is a critical gene in the pathogenesis of AMME, causing midface hypoplasia and elliptocytosis and contributing to early speech and language delay, infantile hypotonia and hearing loss, and may play a role in dysmorphism, nephrocalcinosis and submucous cleft palate." (PMID 27811305, 2017).
Autoimmunity (1 paper, 2025). The occurrence of an immune reaction against the organism's own cells or tissues. "AMMECR nuclear protein 1 (AMMECR1, Gene ID: 9949) can cause dysregulation of immune-related metabolic pathways, making it more susceptible to autoimmunity." (PMID 39891056, 2025).
familial multiple nevi flammei (1 paper, 2008). A congenital vascular malformation in the skin (birthmark) characterized by the presence of dilated capillaries. "Notably, for three OMIM phenotypes (163000, familial multiple nevi flammei; 268700, saccharopinuria; 300195; AMMECR1) our predictions include the actual disease genes that, although not yet correctly annotated in OMIM, have been found to be mutated in patients." (PMID 18369433, 2008).
Intellectual disability (1 paper, 2017). "Our study shows that a single missense mutation in AMMECR1 causes a phenotype of midface hypoplasia, mild intellectual disability and the presence of elliptocytes, previously reported as part of a contiguous gene deletion syndrome." (PMID 27811305, 2017).
X-linked intellectual disability (1 paper, 2022). An X-linked intellectual deficiency in which not enough information is known, reported or published to indicate whether a gene causes non-syndromic or syndromic presentations. "It is reported that AMMECR1 is associated with growth, bone, and heart alterations; CLDN11 is an epigenetic biomarker for malignancy, and THOC2 mutations are related to X-linked intellectual disability." (PMID 35879975, 2022).
cancer (1 paper, 2023). A tumor composed of atypical neoplastic, often pleomorphic cells that invade other tissues. "The function of AMMECR Nuclear Protein 1 (AMMECR1) has been shown to inhibit apoptosis and to promote cell cycle progression in cancer cells." (PMID 36680249, 2023).
tumor (1 paper, 2022). "In the HPA data, compared with normal tissues, DHRS13, PLEKHH1were expressed at medium to high levels in tumor tissues, while the expression of PSMB9, and LRRN2 was significantly up-regulated in OC samples, and AMMECR1, KIAA0100 slightly downregulated in OC samples." (PMID 36307842, 2022).
AMMECR1 also shares sentences with these, for which no sentence is quoted: cataract (1 paper); colon cancer (1); developmental delay (1); Hypercalciuria (1); myopia (1); saccharopinuria (1); Strabismus (1).